MMP9 (matrix metallopeptidase 9)
Diseases named in the same sentence as MMP9 in open-access papers (continued):
Sharing a sentence is not in itself a finding about the gene and the disease.
infection (continued). "Additionally, we found that the infection may induce migration or suppress cellular migratory properties and migratory markers (i.e., VIM and MMP9)." (PMID 39427065, 2024). "Matching the data collected during the physical characterization of the NTHi-NHNE infection, expression levels of key chemo- and cytokines (e.g. CXCL8, IL-6, IL-1β, CCL3, CXCL1 & CXCL2) and genes involved in ECM remodelling and inflammation (PLAU, Serpine1, MMP9) increased further on day14." (PMID 38990812, 2024). "There was no increase in the level of MMP-7 or MMP-9 after infection." (PMID 37939119, 2023). "Specifically, MMP9, MMP8, and MMP14-proteolysis of IL-8, which is also upregulated in LGMDD2 patients, may lead to an increase in its chemotactic potency by guiding the neutrophils to the site of injury or infection." (PMID 35646913, 2022). "Considering the antagonistic functionality of MMP9 and TIMP-1, these data suggest that our control animals may still be actively remodeling lung tissue to combat infection, while the UA-treated animals with altered IL-17 signaling may be resolving the lung environment to repair functionality." (PMID 34869750, 2021). "By immunofluorescence microscopy, infection downregulates the expression of E-cadherin while upregulating the EMT markers smooth muscle actin (SMA), the matrix-degrading enzyme matrix metalloproteinase-9 (MMP9), fibronectin, and the transcription factors SNAIL1/2 and ZEB183,84." (PMID 31249676, 2019). "We hypothesize that T. solium stimulates the production of MMP-9 as a means of enhancing epithelial permeability in order to pass restrictive biological barriers like the intestine and the BBB during early stages of infection." (PMID 30870421, 2019). "However, the role of miR-1303 in CNS-related diseases has not been reported; therefore, based on the target interaction between miR-1303 and MMP9, we aimed to further investigate the effects of miR-1303 on changes in BBB permeability in HUVECs following CA16 infections." (PMID 30228270, 2018). "However, the same study showed that mmp9 was largely expressed by distal neutrophils, rather than at the site of infection." (PMID 28747644, 2017). "Furthermore, mRNA expression of both MMP2 and MMP9 in the B.suis.S2 infection group was not significantly different from the non-infected group." (PMID 26904517, 2016). "Likewise, in fetal membranes from women with spontaneous preterm labour (with and without infection), nobiletin treatment decreased pro-inflammatory cytokine expression and release, and MMP-9 gene expression and secretory pro MMP-9 levels." (PMID 25238390, 2014). "However, since mycetoma is a localized infection, a localized reduction of TIMP-1 could result in higher MMP-9 levels in the lesion, which, in its turn, could be found in serum." (PMID 24675764, 2014). "MMP9 is not expressed in healthy lungs, but may be released under inflammatory conditions (such as infections and neoplastic diseases) by macrophages, mast cells, lymphocytes, and neutrophils." (PMID 22496659, 2012). "Infection of chorioamniotic membranes with E. coli induces an increase in the secretion of inactive forms and an association to ECM of active forms of MMP-2 and MMP-9 without changes in TIMP-1, -2, and -4." (PMID 21266053, 2011). "The MMP-9 cutoff value used for predicting the presence or absence of infection was 13.6 ng/mL." (PMID 20706662, 2010). "Furthermore, the only very preterm CMP included in the study displayed very high concentrations of MMP-8 and MMP-9 even though neither the mother nor the newborn showed signs of an infection." (PMID 20868473, 2010). "However, infection or inflammation may amplify the action of LMW-HAs via interactions with hyaladherins, leading to an increase in the secretion of cytokines (TNF-α, IFN-β, IL-6), chemokines (IL-8), ROS, or enzymes (NE, MMP-9, MMP-10, MMP-12)." (PMID 35625586, 2022).
infection (continued). "Thus, we speculated that the CNS injuries induced by CA16 infection are derived from direct penetration of the BBB by CA16 and that the molecular mechanism of BBB penetration by CA16 is related to the deregulation of junctional complexes via MMP9." (PMID 30228270, 2018). "After infection, CD147, HDAC4 and MMP-9 mRNA levels reduced over time in association with increased miR-22 expression which prevents CD147 protein induction by maintaing its levels unchanged, and reduces HDAC4 and MMP-9 protein levels after infection in pBECs from non-asthmatics." (PMID 30068332, 2018). "In contrast, levels of MCP-1/CCL2, NGAL, sTNFRSF1A, CXCL9, MMP-9, lactoferrin, and IL-1α did not significantly change in patients between critical disease in the ICU and upon infection recovery post-ICU." (PMID 33232303, 2021). "We observed increased expression of MMP-9, but not TIMP-1 or MMP-2, in both CHME-3 and ARPR-19 cells following infection with P. aeruginosa strains." (PMID 32423093, 2020). "MMP-9 protein levels reduced (P = 0.014) after IAV H1N1 infection (24 h) in pBECs from non-asthmatics but were not affected by infection in cells from asthmatics." (PMID 30068332, 2018). "The first profile includes factors that are not affected by infection, such as G-CSF, VEGF-A, MMP-2, and MMP-9 in the decidua and VEGF-A, MMP-2 in the placenta." (PMID 30420629, 2018). "Eight of them (FN1, ALB, CTSL1, OTFB, LYZ, CATHL1, MMP9, LECT2) did not change their expression at the level of transcription and transcripts of 3 of them (RSFR, LYG2, CSTC) even increased following infection." (PMID 28623956, 2017). "Though MMP9 levels correlate with RSV disease severity, its precise role in the pathogenesis of this infection has not previously been determined." (PMID 26284919, 2015). "Upon infection or stimulation with inflammatory cytokines, TIMP production by astrocytes usually does not increase to the same extent as that of MMP-9, thus resulting in an increased MMP/TIMP ratio." (PMID 23587438, 2013). "However, our screening also identified invasion- and migration-related genes that were not significantly modulated upon infection (i.e., PAPPA, SNAIL, MMP9, MMP11, ICAM1, CTNNB1, and CDH2)." (PMID 41450565, 2025). "Unlike the invasion mechanisms of protozoans, during infection by the nematode A. cantonensis, an increase in Cav-1 expression in the brain and through the TLR4/MyD88 signaling pathway to activate MMP-9 leads to degradation of tight junction proteins (Zo-1 and claudin-5)." (PMID 38922036, 2024). "As both WNV and USUV-infected in vitro BBBs showed comparable measures of barrier function to mock, the reduction in MMP-9 and CCL2 concentrations was therefore not sufficient to induce a direct, detectable decrease in permeability of the barrier as a response to infection." (PMID 40295794, 2024). "Also, MMP-9 expression and activity are congruent with CD147 and HDAC4 expression in pBECs after infection particularly in cells from non-asthmatics." (PMID 30068332, 2018). "Interestingly, the gut microbiome was altered in wild type mice following infection but not in MMP-9−/− mice, implicating a role for MMP-9 in the depletion of microbial diversity in the gut, after infection." (PMID 25948887, 2015). "However, despite the robust induction of MMP-9 and PE in response to Hib, no PGP was detectable at any time post infection." (PMID 26400771, 2015). "Contrary to what happens for MMP-9, MMP-2 activity did not change during infection." (PMID 25436884, 2013). "Moreover, RECK regulates MMP9 and exerts its effects primarily through suppression of WNT7A/WNT7B, but regulation of neither Wnt7a nor Wnt7b regulation was observed in our gene microarray dataset, and scRNA-Seq did not detect Wnt7a nor Wnt7b expression, before or after infection, in any ME cells." (PMID 36092940, 2022).
cardiovascular diseases (137 papers, 2009 to 2026). "Matrix metalloproteinase 9 (MMP-9) C(-1562)T gene polymorphism has been considered a risk factor for cardiovascular disease (CVD)." (PMID 38002605, 2023). "Matrix metalloproteinase 9(MMP9), also known as gelatinase B, has been widely studied in cardiovascular disease due to its association with plaque instability." (PMID 35842645, 2022). "The gelatinases MMP‐2 and MMP‐9 have a central role in cardiovascular disease; they are reportedly associated with heart tissue remodeling and were shown to be increased in the failing myocardium." (PMID 31932967, 2021). "Another study demonstrated a significant association between salivary levels of MMP-9 and subclinical cardiovascular diseases, more precisely carotid intima-media thickness, in 250 individuals." (PMID 30726210, 2019). "MMP-9 regulates neutrophil migration across the basement membrane, and has been associated with cardiac pathological remodeling and fibrosis in cardiovascular disease." (PMID 30524357, 2018). "Our results not only determined MMP-9 as a risk factor for cardiovascular diseases in OSAS patients, but also showed the possible involvement of hypoxia-MMP-9-β2AR signaling axis." (PMID 29693002, 2018). "By analyzing the clinical outcomes with MMP-9 expression, we demonstrated that high serum MMP-9 in OSAS patients was a risk factor for occurrence of cardiovascular diseases." (PMID 29693002, 2018). "Both MMP-2 and MMP-9 are involved in extracellular matrix remodeling, and have been implicated in increased susceptibility to cardiovascular diseases." (PMID 27295295, 2016). "In addition, Gastrodin downregulates the expression of MMP-9, which is a high-risk marker for cardiovascular diseases." (PMID 41282615, 2025). "Moreover, MMP9 polymorphisms are associated with genetic susceptibility to cardiovascular disease among individuals with T2DM." (PMID 41516018, 2025). "Interestingly, MMP-9 expression is also a risk factor for cardiovascular diseases in patients with OSA." (PMID 36552999, 2022). "Importantly, polymorphisms of the MMP genes (including MMP9) were suggested to determine the susceptibility to cardiovascular diseases and their complications in various populations, including Caucasians of Central Russia." (PMID 34492072, 2021). "MMP9 has been shown in many studies to be significantly associated with cardiovascular disease." (PMID 34239024, 2021). "Based on the prospective studies, serum levels of MMP-9 could confer a tool to estimate the mortality risk during the cardiovascular diseases." (PMID 32429880, 2020). "MMP-9 activity is highly dependent on its expression level, and functional genetic polymorphisms in the MMP-9 gene might influence MMP-9 concentrations, conceivably modifying the susceptibility to cardiovascular diseases (CVD)." (PMID 27829825, 2016). "Given that MMP-9 may be implicated in the pathogenesis of both depressive and cardiovascular disorders, we also investigated whether there was a relationship between MMP-9/TIMP levels and depressive symptomatology." (PMID 25153995, 2014). "TIMP-1 displays the highest affinity for MMP-9, which plays a significant role in immune cell function and fibrosis in cardiovascular disease." (PMID 41463322, 2025). "Betulinaldehyde, a triterpenoid with diverse biological activities, inhibits proliferation, migration, and phenotypic transformation of vascular endothelial cells and downregulates MMP9 expression, contributing to cardiovascular disease treatment." (PMID 39950029, 2025). "MMP-9, one of the most thoroughly researched MMPs, regulates fibrosis- and inflammation-related structural modification processes in cardiovascular disease." (PMID 38481883, 2024). "Inflammation and cardiovascular disease are associated with expressions of ANP, cTnT, NOS3, MMP-9, and IL-6 genes." (PMID 38348351, 2023). "MMP-9 is elevated in OSA patients and correlates with OSA severity and associated risk of cardiovascular disease." (PMID 38046221, 2023).
cardiovascular diseases (continued). "The results show that curcumin can prevent cardiovascular diseases by declining the expression and activity of MMP-9." (PMID 37175113, 2023). "Studies have found that neutrophil gelatinase-associated lipocalin (NGAL) and NGAL/matrix metalloproteinase (MMP)-9 complexes act as pro-inflammatory factors in cardiovascular diseases." (PMID 37521280, 2023). "Matrix metalloproteinase 9 (MMP9) has been shown to be associated in the pathogenesis and progression of cardiovascular diseases." (PMID 37818163, 2023). "Recently, a clinical study demonstrated elevated MMP9 concentrations in serum and saliva of patients with cardiovascular disease." (PMID 36077021, 2022). "These associations between MMP9 or MMP12 and cardiovascular disease indicate that more basic research and clinical studies are needed to confirm the diagnostic significance and therapeutic potential of MMP9 and MMP12." (PMID 35842645, 2022). "MMP2 and MMP9 belong to the most frequently analyzed MMPs in relation to HF syndrome and other cardiovascular diseases." (PMID 35885988, 2022). "MMP9 and Tissue inhibitors of metalloproteinases 1 (TIMP1) were known to be associated with the risk of cardiovascular disease and several cancers." (PMID 35246549, 2022). "Pathological ventricular remodeling is an important pathological change in cardiovascular diseases, and MMP-9 is the main protease involved in ventricular remodeling." (PMID 35222898, 2022). "At present, MMP9 is considered a biomarker of AS vulnerable plaques and has been suggested as a potential therapeutic target for cardiovascular disease." (PMID 35935949, 2022). "In patients, MMP-9 increase in cardiovascular disease can be driven by multiple factors, one of which is via promoter-activating single nucleotide polymorphisms (SNPs)." (PMID 33579197, 2021). "MMP-9 is involved in different types of pathological remodeling including inflammatory mechanism, cardiovascular disease, and oncologic processes." (PMID 34458302, 2021). "supporting MMP‐9 as an early stage biomarker of poor outcome in cardiovascular disease potentially reflecting atherosclerotic plaque rupture and myocardial tissue destruction." (PMID 31932967, 2021). "As expected, among the cardiovascular disease related genes, MMP9, TNF, IFN-ɣ, and VCAM1 genes were the top up-regulated genes in ILC1s was earlier shown to play an important role in the occurrence of post-PCI restenosis." (PMID 32198366, 2020). "We further demonstrate that RIH or glucose fluctuations in vitro upregulate the expression of IRF5 together with markers of inflammation and the cardiovascular disease marker MMP-9." (PMID 32806763, 2020). "Mmp9 is also used as a marker to assess the severity of cardiovascular diseases – an increased level indicates a poor prognosis." (PMID 33061247, 2020). "It is well known that Mmp9 plays a key role in the development of cardiovascular diseases as well as cardiac remodeling by altering ECM, fibroblast migration, collagen and cytokine production, and stimulating cell differentiation." (PMID 33061247, 2020). "MMP9 plays critical roles in pathological processes of cardiovascular diseases that involve tissue remodeling, inflammation, or fibrosis." (PMID 29768431, 2018). "One of the MMP family member, MMP9, has been shown to involve in the pathogenesis of cardiovascular diseases." (PMID 28390432, 2017). "The prospective researches have shown that plasma MMP-9 contents can serve as the prediction indicator for the cardiovascular diseases mortality." (PMID 27375491, 2016). "Age-dependent alterations in MMPs and TIMPs have been studied in skin and cardiovascular disease, and increased activities of MMP2 and MMP9 have been associated with tenocyte aging." (PMID 27391467, 2016). "The unique structure of SalA and its relative potency on MMP-9 inhibition afford a great deal of potential for further optimization of this natural compound into therapeutics for cardiovascular disease." (PMID 23533637, 2013).
cardiovascular diseases (continued). "Salvianolic acid B (SalB) from Salviae mitiorrhizae, which has been widely used in China for the treatment of cardiovascular diseases, is a potential candidate for therapeutic intervention of LV remodeling targeting matrix metalloproteinase-9 (MMP-9)." (PMID 20735854, 2010). "It is quite hopeful that the unique structure of SalB, and its relative selectivity towards MMP-9, will enable us to explore the structure-activity relationship to identify more specific and safer MMP-9 inhibitors for the treatment of cardiovascular disease." (PMID 20735854, 2010). "Elevated levels of MMP-9 indicate a poor prognosis for cardiovascular diseases." (PMID 41282615, 2025). "One possible explanation is the greater inter-individual variability in MMP-9 activity, which may be influenced not only by AD pathophysiology but also by other age-related comorbidities, such as cardiovascular diseases." (PMID 41009358, 2025). "Similarly, the research conducted by Szymanowski highlights the importance of MMP-9 as a potential connection between stress and cardiovascular disease." (PMID 38254696, 2024). "MMPs are associated with cardiovascular diseases, in particular MMP-2 and MMP-9." (PMID 32545475, 2020). "Hence, MMP‐9 can be used in clinical diagnosis indicator of cerebrovascular and cardiovascular diseases." (PMID 32533644, 2020). "MMP-9 plays an important part in various cardiovascular diseases and can degrade components of the extracellular matrix, leading to weakening of the fibrous cap and development of cardiovascular and cerebrovascular diseases, including IS, atherosclerosis, and neuroinflammation." (PMID 30992065, 2019). "Finally, we performed cellular and molecular experiments to investigate the possible functional mechanisms of MMP-9 in promoting cardiovascular diseases of OSAS patients." (PMID 29693002, 2018). "Therefore, the cleavage of β2AR by MMP-9 can also partially explain the high prevalence of cardiovascular diseases." (PMID 29693002, 2018). "The involvement of MMP-9 in cardiovascular diseases has been well-acknowledged." (PMID 29693002, 2018). "Furthermore, MMP9 SNP rs3918242 and circulating MMP9 level are associated with coronary heart disease (CHD) progression and MI, arterial stiffness and cardiovascular disease mortality in patients with CHD, while the mechanisms are not completely understood." (PMID 28390432, 2017). "To date, evidence has shown that MMP-2 and MMP-9 are the only two genes which epigenetic modification may contribute to the development of cardiovascular disease." (PMID 27295295, 2016). "Given the role of MMP9 in mobilization of hematopoietic stem and (endothelial) progenitor cells, our findings confirm NO levels in the BM as a potential modifiable upstream target to promote E(PC) mobilization in cardiovascular disease." (PMID 23554866, 2013). "Indeed, reduced MMP-9 activity diminishes macrophage trans-ECM migration and protects from local inflammation and inflammation-associated cardiovascular disease." (PMID 20463885, 2010). "Additionally, exploring ITE’s role in other MMP-9–driven inflammatory conditions, such as cardiovascular disease and autoimmune disorders, may further validate its potential as a novel anti-inflammatory therapeutic agent." (PMID 40565127, 2025). "Moreover, inhibiting MMP-9 during the acute stages of cardiovascular disease may provide favorable outcomes, but limiting MMP-9 as the disease progresses may curtail compensatory remodeling and contribute to a progression into HF." (PMID 36982525, 2023). "The dynamics and direction of changes at various stages of the cardiovascular disease continuum in the serum fibrosis markers, MMP-9 and TIMP-1 systems, may reflect an increase in fibrotic and decrease in antifibrotic processes already at the preclinical stage of HF." (PMID 33224989, 2020).